CLEC4E (C-type lectin domain family 4 member E)
Diseases named in the same sentence as CLEC4E in open-access papers:
CLEC4E is named in the same sentence as 54 diseases in open-access papers, as found by Europe PMC text mining. Sharing a sentence is not in itself a finding about the gene and the disease. The quoted sentences say what the papers report.
lung carcinoma (2 papers, 2021 to 2022). "The lung cancer-specific cfRNAs IL1R2 and CLEC4E are related to immune regulation." (PMID 35816095, 2022).
osteosarcoma (2 papers, 2022 to 2024). A usually aggressive malignant bone-forming mesenchymal neoplasm, predominantly affecting adolescents and young adults. "Furthermore, scRNA-seq analysis of six treatment-naïve osteosarcoma tumors, combined with a dataset of 22,035 cells from six osteosarcoma tumors, demonstrated that MDSCs were among the most abundant in the immunosuppressive milieu, as evidenced by MDSC hallmark genes (VCAN, CLEC4E, and CSF3R)." (PMID 39359731, 2024). "Interestingly, B cells in TNF‐Tg SBM also show increased levels of C‐type lectin domain family gene CLEC4D and CLEC4E, suggesting that the CLEC11A+ B cells in osteosarcoma may have similar biological functions as the TNF‐Tg SBM‐derived B cells." (PMID 36305631, 2022).
acute kidney injury (1 paper, 2022). Sudden and sustained deterioration of the kidney function characterized by decreased glomerular filtration rate, increased serum creatinine or oliguria. "An M1 macrophage profile is also present during acute kidney injury and can be targeted by modulation of heparin-binding protein expression or the targeting of CLEC4e/Mincle-Syk selectively on macrophages." (PMID 35681519, 2022).
Arthritis (1 paper, 2020). Inflammation of a joint. "The BN strain shares alleles with DA only in the Clec4e locus, whereas the remaining sequence of the BN Clec4bde region is shared with E3, the arthritis protective haplotype." (PMID 32497089, 2020).
atherosclerosis (1 paper, 2022). A disease characterized by the build-up of fatty material and calcium deposition in the arterial wall resulting in partial or complete occlusion of the arterial lumen. "According to a recent study, Clec4e expressed on macrophages can detect necrotic cells and promote local inflammation, which promotes atherosclerosis." (PMID 36186997, 2022).
chlamydia (1 paper, 2015). "We found evidence that one receptor (CLEC4E) may be upregulated in koalas with chlamydia and found a non-significant trend for upregulation of several NK genes." (PMID 26471184, 2015).
chlamydia infection (1 paper, 2015). "This analysis revealed that one of these four, CLEC4E, may be upregulated in response to chlamydia infection." (PMID 26471184, 2015).
gastritis (1 paper, 2023). Inflammation of the stomach. "On the other hand, H. pylori metabolites were reported that exacerbate gastritis through C-type lectin receptors such as C-type lectin domain family 4 member (CLEC4E)." (PMID 36602319, 2023).
hepatocellular carcinoma (1 paper, 2023). A malignant tumor that arises from hepatocytes. "Clec4e is an important regulator of the immune response, and higher levels of its expression are correlated with increased immune cell infiltration in hepatocellular carcinoma." (PMID 36765634, 2023).
idiopathic pulmonary fibrosis (1 paper, 2025). Idiopathic pulmonary fibrosis (IPF) is a nonneoplastic pulmonary disease that is characterized by the formation of scar tissue within the lungs in the absence of any known cause. "Furthermore, the authors found unusual levels of certain genes in the red module associated with idiopathic pulmonary fibrosis, specifically S100A12, S100A9, CLEC4E, CRIP1, and IL1R2." (PMID 40782499, 2025).
lupus nephritis (1 paper, 2012). Glomerulonephritis in the context of systemic lupus erythematosus. "Several studies suggest that TLR signalling is important in the pathogenesis of lupus nephritis, while the role of Clec4e in this context is undetermined." (PMID 22479529, 2012). "We demonstrate that exposure of chromatin significantly up-regulate Toll like receptors and Clec4e in mice, and also but less pronounced in patients with lupus nephritis treated with immunosuppresants." (PMID 22479529, 2012). "Since Clec4e regulation in lupus nephritis is not determined previously, we also analysed if this receptor was selectively up-regulated in nephritic kidneys or in other organs expressing this protein, like the spleen." (PMID 22479529, 2012). "In sum, the vector that point at chromatin-IgG deposits in GBM are clustered with vectors pointing at TLR7–9, Clec4e, MMP2 and MMP9, indicating an interdependency between them, while the DNaseI vector points the opposite direction due to its negative correlation with advanced lupus nephritis." (PMID 22479529, 2012).
melanoma (1 paper, 2021). A malignant, usually aggressive tumor composed of atypical, neoplastic melanocytes. "We focused on the potential prognostic value of EDN3, CLEC4E, SRPX2, KIR2DL4, UBE2L6, and IFIT2 as immune scores for melanoma patients." (PMID 34660598, 2021). "The IHC staining results showed that Ube2L6, SRPX2, and IFIT2 were expressed at higher levels, while CLEC4E, END3, and KIR2DL4 were expressed at lower levels in 25 melanoma specimens." (PMID 34660598, 2021). "According to immunohistochemistry staining results, Ube2L6, SRPX2, and IFIT2 were expressed at higher levels, while CLEC4E, END3, and KIR2DL4 were expressed at lower levels in 25 melanoma specimens." (PMID 34660598, 2021).
myocardial infarction (1 paper, 2017). Gross necrosis of the myocardium, as a result of interruption of the blood supply to the area, as in coronary thrombosis. "A similar level of scarring was observed between the hearts of Clec4e−/− mice (n = 11), Clec4e+/− littermates and WT animals (combined n = 14) at one month following myocardial infarction." (PMID 27492949, 2017).
Obesity (1 paper, 2022). Accumulation of substantial excess body fat. "Excess FFAs also activates Toll—Like receptor 4 (TLR4) in macrophages and recruits the macrophage-inducible C-type lectin (CLEC4E), which is essential for the expression of fibrosis-related genes and regulates obesity-induced adipose tissue fibrosis." (PMID 36496995, 2022).
pneumonia (1 paper, 2025). An acute, acute and chronic, or chronic inflammation focally or diffusely affecting the lung parenchyma, caused by an infection in one or both of the lungs (by bacteria, viruses, fungi, or mycoplasma.). "Gene expression analysis revealed significant upregulation of immune-related markers (TLR2, CLEC4E, PTX3, CXCL8, IL15RA) and notable SNP variations associated with pneumonia susceptibility." (PMID 40559821, 2025). "Using PCR-DNA sequence verdicts, the TLR2 (354 bp), CLEC4E (443 bp), PTX3 (363 bp), CXCL8 (300 bp), SOCS3 (480 bp) and IL15RA (378 bp) genes were found to have different SNPs in the amplified DNA bases linked to pneumonia." (PMID 40559821, 2025). "The genes TLR2, CLEC4E, PTX3, CXCL8, and IL15RA exhibited significantly higher expression levels in pneumonia-affected ewes compared to healthy controls." (PMID 40559821, 2025). "This study used a PCR-DNA sequencing technique to characterize the immunological (TLR2, CLEC4E, PTX3, CXCL8, SOCS3 and IL15RA) genes in ewes with pneumonia and healthy ewes." (PMID 40559821, 2025).
Sepsis (1 paper, 2024). Sepsis is defined as life-threatening organ dysfunction caused by a dysregulated host response to infection. "The Venn diagram shows that a total of eight overlapping genes were discovered between ACSL4 co-expression genes and sepsis, including GK, CLEC4E, ACSL1, TGFBR3, ADAM9, AZI2, BCAT1, and CYP1B1." (PMID 39262873, 2024). "There is a lack of definitive research data on the specific role of CLEC4E in disulfidptosis or sepsis." (PMID 39262873, 2024).
Stroke (1 paper, 2025). Sudden impairment of blood flow to a part of the brain due to occlusion or rupture of an artery to the brain. "In this study, we found that all three biomarkers, ABCA1, CLEC4E, and IRS2, were associated with the activation of NET formation and infiltration levels of neutrophils in the IS, implying their importance in stroke." (PMID 40264650, 2025). "Although CLEC4E has not been reported in patients with stroke, other members of this superfamily have been shown to play important roles." (PMID 40264650, 2025).
tuberculosis (1 paper, 2021). A chronic, recurrent infection caused by the bacterium Mycobacterium tuberculosis. "In previous studies, CLEC4E was found to be related to tuberculosis and could be used to constrain tuberculosis through autophagy against drug-resistant strains." (PMID 34660598, 2021).
viral infections (1 paper, 2023). "Well characterized immune regulators, like Clec4e, H2q6 and Ifitm3, have defined roles in LACV or other viral infections." (PMID 37202395, 2023).
infection (19 papers, 2015 to 2025). The state of being infected such as from the introduction of a foreign agent such as serum, vaccine, antigenic substance or organism. "In order to address the immune response to the infection with C. diphtheriae in BMM, Clec4e- and Myd88-deficient cells, the supernatants were collected at 2, 4 and 20 h post-infection for determination of cytokine secretion, such as G-CSF and IL-6, respectively." (PMID 31057086, 2019). "Differential expression analysis in this dataset showed a significant upregulation of four core genes (CCL5, PTGS2, HIF1A, and CLEC4E) in the infection group." (PMID 41039310, 2025). "When examining the in vivo transcriptional response of mammary epithelial cells during the early phases of infection with Staphylococcus aureus, CLEC4E was elevated in other goat investigations." (PMID 40559821, 2025). "Previous research has indicated a significant upregulation of CLEC4E in various tissues following infection of turbot (Scophthalmus maximus) with V. anguillarum and E. tarda." (PMID 39717544, 2024). "In this study, CLEC4E, identified as a key protein, exhibited a significant upregulation of 19.56-fold following infection with N. seriolae." (PMID 39717544, 2024). "Clec4d (MCL) and Clec4e (Mincle) bind to Mtb ligands, (i.e., trehalose 6,6'-dimycolate, a.k.a cord factor) and are upregulated on myeloid cells after infection with other pathogens." (PMID 32544188, 2020). "There was an infection level-dependent down-regulation for clec4e, with the lowest expression in the H-BKD group." (PMID 33193341, 2020). "Expression of clec4e negatively correlated with the infection level, as it was suppressed in the H-BKD group compared with the L-BKD fish." (PMID 33193341, 2020). "In others studies on goats, CLEC4E was up-regulated when was investigated in the in vivo transcriptional response of mammary epithelial cells at the early stages of infection with Staphylococcus aureus." (PMID 29742137, 2018). "Many of the selected genes were immune‐related and play a role in the host response against infection, such as BPI, PRSS33, S100A9, CLEC4E, and so on." (PMID 39692191, 2025). "Previous studies have shown that significant upregulation of CLEC4E was seen in koalas with Chlamydia pecorum infection compared to those without infection." (PMID 36602319, 2023). "In preliminary investigation of expression of four genes of interest, significant upregulation of one gene (CLEC4E) was seen in koalas with C. pecorum infection, compared to those without infection based on Chlamydia PCR." (PMID 26471184, 2015).
tumor (9 papers, 2019 to 2025). "Knockdown of Nidogen-1, but not of Hspg2, in tumor cells reduced their susceptibility to neutrophil cytotoxicity, suggesting that Clec4e/Dectin-1 contribute to the recognition of tumor cells through interaction with Nidogen-1." (PMID 35453656, 2022). "Conversely, within the top 20 upregulated genes, our treatment had significant long-term effects on the tumor suppressors Lman1I, Clec4e, and Parp6." (PMID 36765634, 2023). "To provide further support to the notion that CLRs mediate neutrophil recognition of tumor cells, we pre-incubated the neutrophils with blocking antibodies to Clec4e, Dectin-1 or NKG2D prior to their incubation with the tumor cells." (PMID 35453656, 2022). "We observed that soluble decoy receptors to the CLRs NKG2D, Clec4e and Dectin-1 partly interfered with neutrophil cytotoxicity towards murine tumor cells, suggesting a common ligand on tumor cells." (PMID 35453656, 2022). "In the present study, we identified a role for Clec4e and Dectin-1 on murine neutrophils in facilitating the anti-tumor response." (PMID 35453656, 2022). "Using mouse models of cancer, we have presented data showing that the two CRLs Dectin-1 and Clec4e on neutrophils are co-operating in recognizing Nidogen-1 and Hspg2 on the tumor cell surface." (PMID 35453656, 2022). "In the group of novel hub genes, low expression levels of UBE2L6, KIR2DL4, IFIT2, and CLEC4E were observed in tumor cells, while high expression levels of SRPX2 and EDN3 were found in SKCM." (PMID 34660598, 2021). "Immune-related genes, such as chemokine (Cxcr2), C-type lectin (Clec4e), chemokine ligand (Cxcl3), tumor growth-related genes, galectin-7 (Lgals7), and matrix metallopeptidase 8 (Mmp8), were downregulated by colonization of B. plebeius in colon tissues of the mice exposed to AOM/DSS." (PMID 39804065, 2025). "The expression of MDSC marker genes such as Itgam, S100a9, and Clec4e, and tumor proliferation-associated genes, Ccnd1 (Cyclin D1) and Myc (c-Myc), was enhanced after PGE2-administration, indicating that MDSC expansion and tumor growth are promoted by PGE2." (PMID 36932082, 2023). "Further studies showed that Clec4e and Dectin-1 interact with each other, which might explain the inhibition of neutrophil anti-tumor function by using neutralizing antibodies to either Clec4e or Dectin-1." (PMID 35453656, 2022). "The finding that antibodies to both Clec4e and Dectin-1 reduced tumor cell killing, led us to test whether Clec4e and Dectin-1 could interact with each other, and thus act together." (PMID 35453656, 2022). "However, the expression of CLEC4A, CLEC4D, CLEC4E, CLEC4J (FCER2), CLEC4K (CD207), CLEC4G, CLEC4H1, CLEC4M, and CLEC4H2 decreased with tumor progression." (PMID 34409028, 2021). "In addition, the CLR receptors Dectin-1 and Clec4e on neutrophils interact with Nidogen-1/Hspg2 expressed on the tumor cell surface, some of which also interact with the tumor RAGE, thus bridging the neutrophils to the tumor cells." (PMID 35453656, 2022). "In addition to the well-documented expression of Clec4e and Dectin-1 on neutrophils, we noticed that neutrophils also express the NKG2D receptor, which was previously reported to play a role in NK recognition of tumor cells." (PMID 35453656, 2022). "Here we show that blocking antibodies to the C-type lectin receptors (CLRs) Clec4e and Dectin-1, but not those to NKG2D, attenuated murine neutrophil cytotoxicity towards murine tumor cells, suggesting a contributing role for these CLRs in neutrophil recognition of tumor cells." (PMID 35453656, 2022).
cancer (7 papers, 2021 to 2025). A tumor composed of atypical neoplastic, often pleomorphic cells that invade other tissues. "In cancer studies, the C-type lectin domain family 4 member E (Clec4e, also known as Mincle) of macrophages was involved in inflammation-related diseases and was strongly associated with fibrosis in adipose tissue, lung, liver and other tissues." (PMID 40044628, 2025). "In contrast, the number of CTLs members namely CLEC3B, CLEC4G/M, and CLEC4E are decreased in cancer cells, which have the potential to be suppressor genes in different cancers." (PMID 38167030, 2024). "We identified heightened expression of TLR2 as well as CLEC5A and CLEC4E in cancer samples in general and in the subgroup." (PMID 38979413, 2024). "Recently, it has been shown that CLEC4E is involved in enhancing the aggressiveness of urothelial cancer, and a new reported inhibitor of cancer cell invasion was identified based on its role in binding to the CLEC4E receptor." (PMID 34692492, 2021).
bacterial infection (1 paper, 2021). "The decreased expression of CLEC4E was associated with bacterial infection and has been observed in several studies." (PMID 34376176, 2021).
inflammation (1 paper, 2021). Aberrant reaction of the microcirculation characterized by movement of fluid and leukocytes from the blood into extravascular tissues. "Two other studies also showed that Clec4e expression increases in macrophages localized to the kidneys during acute renal inflammation, suggesting Clec4e perpetuates proinflammatory cytokine signaling and cell death in the kidney." (PMID 35295146, 2021).
kidney disease (1 paper, 2025). "SYK is activated downstream of DAMP-sensing C-type lectin receptors such as CLEC4E (Mincle, Clec4e) and CLEC7A (Dectin-1, Clec7a) that have been implicated in kidney disease." (PMID 40857403, 2025).
CLEC4E also shares sentences with these, for which no sentence is quoted: Gaucher disease (2 papers); ischemic stroke (2); rheumatoid arthritis (2); acute coronary syndrome (1); allergic contact dermatitis (1); Autoimmunity (1); brain injury (1); Cirrhosis (1); co-infection (1); coronary artery disease (1); diabetes (1); diabetic nephropathy (1); helminth infections (1); Hepatitis (1); Hypertension (1); immune diseases (1); infarction (1); infectious disease (1); lung adenocarcinoma (1); lung squamous cell carcinoma (1); nematodes infection (1); non-small cell lung carcinoma (1); pancreatic ductal adenocarcinoma (1); parasitic infections (1); Parkinson disease (1); periodontitis (1); psoriasis (1); relapsing-remitting MS (1); rheumatic diseases (1).